PPP4R3C (protein phosphatase 4 regulatory subunit 3C)
Synonyms: PPP4R3CP; SMEK3P; FLJ32867; FLFL3P; smk1
Tractability: No criterion of Open Targets' tractability assessment is met for any kind of drug.
Gene: Protein-coding gene on chromosome X (27,460,207 to 27,463,341, reverse strand). Ensembl gene ENSG00000224960.
Gene Ontology:
Molecular function: protein phosphatase activator activity; protein phosphatase regulator activity
Biological process: DNA damage response; regulation of double-strand break repair
Cellular component: nucleus
Homologues: Orthologues: chimpanzee PPP4R3C (98% identical), pig PPP4R3C (64% identical), tropical clawed frog ppp4r3b (61% identical), rabbit PPP4R3C (54% identical), guinea pig PPP4R3C (53% identical), mouse Ppp4r3c1 (48% identical), rat Ppp4r3cl2 (48% identical), rat Ppp4r3cl3 (48% identical), rat AABR07038788.1 (47% identical), mouse Ppp4r3c2 (46% identical), Drosophila melanogaster flfl (42% identical), Caenorhabditis elegans smk-1 (32% identical), and 1 more. Paralogues in human: PPP4R3B (62% identical), PPP4R3A (52% identical).
Diseases named in the same sentence as PPP4R3C in open-access papers:
PPP4R3C is named in the same sentence as 1 disease in open-access papers, as found by Europe PMC text mining. Sharing a sentence is not in itself a finding about the gene and the disease.
PPP4R3C shares sentences with these, for which no sentence is quoted: tumor (1 paper).